SIRT1 (sirtuin 1)
Diseases named in the same sentence as SIRT1 in open-access papers (continued):
Sharing a sentence is not in itself a finding about the gene and the disease.
renal fibrosis (continued). "Further studies have revealed that the activation of SIRT1 promotes the activation of renal fibroblasts and exacerbates renal fibrosis." (PMID 39335456, 2024). "SIRT1 is a potential therapeutic target for renal fibrosis and is involved in aging, energy homeostasis, autophagy, mitochondrial biogenesis, and apoptosis." (PMID 39335456, 2024). "This review discusses the role of SIRT1 in renal fibrosis by examining its involvement in the various biological processes associated with its development." (PMID 39335456, 2024). "According to previous reports, upregulation of SIRT1 reduces endoplasmic reticulum stress and renal fibrosis." (PMID 39335456, 2024). "Collectively, these results indicated that OA repressed renal fibrosis by activating the expression of Sirt1 and blocking the TGF-β/Smad3 pathway." (PMID 39687299, 2024). "Quercetin has been reported to reduce RTECs senescence and alleviate renal fibrosis by activating Sirt1/PINK1/Parkin-mediated mitochondrial phagocytosis." (PMID 38347622, 2024). "Various mechanisms have been suggested to elucidate the pathogenetic relationship between SIRT1 and the initiation of renal fibrosis." (PMID 39911234, 2024). "This manuscript explores the potential of SIRT1 as a therapeutic target for renal fibrosis and offers new perspectives on treatment approaches and prognostic assessments." (PMID 39335456, 2024). "SRT1720, a potent activator of SIRT1, promotes renal fibrosis via increased phosphorylation of epidermal growth factor receptor (EGFR) and platelet-derived growth factor receptor β (PDGFRβ)." (PMID 39335456, 2024). "Future studies should focus on developing more specific SIRT1-targeted therapies and drug delivery systems for the treatment of renal fibrosis." (PMID 39335456, 2024). "Sirt1 is a key regulatory factor in various cellular processes, and it participates in the regulation of renal fibrosis." (PMID 39687299, 2024). "Based on the protective effect of SIRT1 against renal fibrosis, it is important to investigate SIRT1 agonists with higher specificity." (PMID 39335456, 2024). "The major findings of this study showed that OA ameliorates renal fibrosis by activating the expression and activity of Sirt1 and inhibiting the TGF-β/Smad3 signaling pathway." (PMID 39687299, 2024). "Further investigation revealed that SIRT1 significantly enhanced the activity of the Keap1/Nrf2/ARE pathway to alleviate advanced glycation end-product-induced renal fibrosis." (PMID 39335456, 2024). "SIRT1 knockdown increases renal fibrosis and destroys renal function, whereas SIRT1 overexpression decreases TGF-β-induced extracellular matrix production and expression." (PMID 39080683, 2024). "Quercetin has been observed to attenuate senescence in RTECs and mitigate renal fibrosis through the activation of Sirt1/PINK1/Parkin-mediated mitophagy." (PMID 39911234, 2024). "Previous studies have reported that Sirt1 can inhibit renal fibrosis induced by TGF-β1 signal transduction by deacetylating Smad3 and Smad4." (PMID 38446387, 2024). "Targeting SIRT1-mediated ferroptosis is a promising research direction for the treatment of renal fibrosis." (PMID 39335456, 2024). "This review provides a comprehensive summary of the current understanding and advancements in the field; specifically, the biological roles and mechanisms of SIRT1 in regulating renal fibrosis progression." (PMID 39335456, 2024). "The SIRT1-specific agonist SRT1720 has the potential to improve renal fibrosis and salvage renal function in children with CHn." (PMID 37534327, 2023). "Promoting SIRT1 expression can inhibit pyroptosis of renal tubular epithelial cells, reduce the release of IL-18 and IL-1β, and alleviate the progression of renal fibrosis in children with CHn." (PMID 37534327, 2023).
renal fibrosis (continued). "SRT1720 can protect the proliferation ability of renal tubular epithelial cells by promoting SIRT1 expression, and maintaining cell proliferation ability is also a possible mechanism by which SIRT1 improves renal fibrosis." (PMID 37534327, 2023). "SIRT1 has also been shown to play a role in renal fibrosis via the downregulation of matrix metalloproteinase-14 (MMP14)." (PMID 37371668, 2023). "Resveratrol has been reported to ameliorate renal fibrosis by enhancing the binding between Sirt1 and Smad3, reducing acetylation levels of Smad3." (PMID 37866886, 2023). "AMCZ markedly lowered the elevated levels of p-JNK, FN, Col-IV, α-SMA, IL-1β, and TNF-α in CKD rats, suggesting AMCZ attenuated renal fibrosis and inflammation through the modulation of SIRT1/JNK signaling pathway." (PMID 37089928, 2023). "It has already been mentioned that salidroside can improve mitochondrial biogenesis and reduce renal fibrosis in diabetic patients by activating the Sirt1/PGC-1α signaling pathway." (PMID 38259279, 2023). "Collectively, rhein protects rats from renal fibrosis by regulating SirT1/STAT3/Twist1 pathway to promote Cpt1a-mediated fatty acid degradation." (PMID 35408745, 2022). "Judging from some studies regarding renal fibrosis, it has been found that activation of SIRT1 can curb TGF-β1/Smad3 expression to alleviate fibrosis." (PMID 35958178, 2022). "In UUO, SIRT1 expression or activation in renal medullary interstitial cells attenuated the expression of COX2 and the subsequent renal fibrogenesis, linking SIRT1 in renal interstitial cells to oxidative stress signaling and renal fibrosis." (PMID 35874713, 2022). "For example, Sal B attenuates epithelial–mesenchymal transition in renal fibrosis rats through activating Sirt1-mediated autophagy, but in cardiac myocytes, it can inhibit autophagy and protect starving cardiac myocytes." (PMID 35991894, 2022). "In this study, we demonstrated that rhein prevents renal fibrosis by promoting Cpt1a-mediated FAO through SirT1/STAT3/Twist1 pathway." (PMID 35408745, 2022). "Deficiency of Sirt1 in endothelial cells increases peritubular capillary rarefaction and aggravates nephrosclerosis, via downregulation of matrix metalloproteinase-14, which indicates a role of SIRT1 in renal fibrosis." (PMID 35795148, 2022). "For example, fucoxanthin mitigates high glucose-induced oxidative stress and inhibits renal fibrosis via the Akt/Sirt1/FoxO3α signaling pathway." (PMID 35126819, 2022). "Nevertheless, a recent study showed that renal fibrosis was inhibited by treatment of UUO mice with the SIRT1/2 inhibitor sirtinol or SIRT1 inhibitor EX527." (PMID 35277012, 2022). "In the UUO and I/R models, SIRT1 activation improved renal fibrosis in proximal tubular cells by deacetylating SMAD3 and SMAD4 and blocking the effect of TGF-β signaling on matrix metalloproteinase-7 (MMP-7), which normally cleaves E-cadherin." (PMID 35277012, 2022). "Here, we present that rhein upregulated Cpt1a-mediated FAO through the SirT1/STAT3/Twist1 pathway to improve renal fibrosis." (PMID 35408745, 2022). "Our previous research indicated that SRT1720 can activate Sirt1 to reduce oxidative stress and renal fibrosis in DN." (PMID 35090502, 2022). "It has also been found in renal fibrosis research studies that raised SIRT1 expression can curb TGF-β1 and Smad3 expression to downsize the occurrence of EMT." (PMID 35958178, 2022). "The studies showed that fucoxanthin can effectively inhibit oxidative stress and exert biological activity as an agonist of Sirt1 or Nrf2 in diseases such as ischemic stroke, subarachnoid hemorrhage, alcoholic liver injury, and renal fibrosis." (PMID 35126819, 2022). "In HK-2 cells, miR-133b and miR-199b targeted SIRT1 for downregulation, leading to the enhanced epithelial to mesenchymal transition and renal fibrosis." (PMID 34097717, 2021). "Deletion of Sirt1 in renal interstitial cells resulted in more severe renal fibrosis in UUO model mice." (PMID 33758176, 2021).
renal fibrosis (continued). "C. cicadae inhibited renal fibrosis progression primarily by decreasing ECM deposition through SIRT1-mediated autophagy." (PMID 35222012, 2021). "To examine the potential roles of SIRT1 in renal fibrosis, we bred SIRT1 CKO mice by crossing floxed Sirt1 mice with TNCCreER mice." (PMID 33758176, 2021). "The regulatory role of SIRT1 to TGF‐β signaling has also been revealed recently, and it is reported that SIRT1 inhibits the TGF‐β/Smad3 pathway to attenuate renal fibrosis." (PMID 33906673, 2021). "Another study then revealed that resveratrol, an activator of Sirt1, attenuated the progress of renal fibrosis both in vitro and in vivo by inhibiting the TGF-β/SMAD3 signaling pathway and reducing the stress caused by reactive oxygen species." (PMID 33906673, 2021). "The result indicated that the stimulated SIRT1 and suppressed peroxidation contributed to renal fibrosis and injury." (PMID 35222012, 2021). "Quercetin at 20 μM improves renal tubular epithelial cell senescence induced by angiotensin II and slowed down renal fibrosis progression by activating Sirt1/PINK1/Parkin pathway." (PMID 34175838, 2021). "In the present study, we demonstrated that the oligo-fucoidan greatly improves renal fibrosis under diabetic condition through inhibition of TGF-β1-activated pro-fibrogenic pathway via activation of Sirt-1, GLP-1R, and Nrf2/HO-1." (PMID 33049944, 2020). "Our study identified that intrarenal delivery of GDNF-AMSC-exos increased the number of PTCs, decreased renal fibrosis, and upregulated SIRT1 expression." (PMID 32802201, 2020). "The beneficial effects of SIRT1 are mediated by its ability to inhibit renal fibrosis, reduce tubular and glomerular cell apoptosis and inflammation, promote autophagy and control blood pressure." (PMID 33362554, 2020). "Recent studies in mouse and in human tumor cell cultures describe that SIRT1 is over-expressed in MSCs and the miR-133b knockdown induced epithelial to mesenchymal transition and renal fibrosis by up-regulation of SIRT1." (PMID 32655835, 2020). "SIRT1 overexpression reduces TGF-β-induced extracellular matrix expression and production; in contrast, SIRT1 knockdown promotes renal function damage and enhances renal fibrosis." (PMID 32811535, 2020). "Excessive activation of NLRP3 inflammasome and down-regulation of Sirt1/Smad3 deacetylation pathway play a significant role in the evolution of renal fibrosis." (PMID 31118021, 2019). "Our data showed that SIRT1 protein expression was reduced in ATRAP-deficient mice, although the relationship between ATRAP deficiency and age-associated renal fibrosis is still not fully understood." (PMID 31719572, 2019). "MiR-133b and miR-199b inhibition suppresses TGFβ1-induced EMT and renal fibrosis by targeting SIRT1 in DN." (PMID 31631065, 2019). "On the other hand, TGF-β1-induced extracellular matrix expression was attenuated by elevated levels of SIRT1, supporting the idea of protective role of SIRT1 in the development of renal fibrosis due to its action on TGF-β/Smad3 signaling." (PMID 30298020, 2018). "Such a result is consistent with recently published data showing that AST-IV and FMR reduce oxidative stress to protect sciatic nerve tissue and reverse renal fibrosis and improve renal function through regulation of autophagy and podocyte epithelial–mesenchymal transition via activating Sirtuin-1." (PMID 39859490, 2025). "The marked reduction of SIRT expression in CKD mice may be explained by the enhanced TGF-β pathway which induces miR-373 expression that targets SIRT1 and enhanced renal fibrosis." (PMID 40514411, 2025). "Furthermore, it also mitigates renal fibrosis by decreasing the senescence of RTECs via the Sirt1/PINK1/mitochondrial autophagy pathway." (PMID 40308781, 2025). "Furthermore, SIRT1’s interaction with eNOS contributed to ameliorating renal fibrosis, as assessed by fibrosis scoring in the UUO model." (PMID 39911234, 2024).
renal fibrosis (continued). "OA could form hydrogen bonds with key the amino acid ASN226 in Sirt1, thereby activating Sirt1, which might also be the reason why OA could resist renal fibrosis." (PMID 39687299, 2024). "In total, these findings suggested that the reduction of renal fibrosis by DSI treatment may be due to the activation of SIRT1 and GPX4." (PMID 39872048, 2024). "Taken together, our results indicated that DSI could protect against ferroptosis to attenuate renal fibrosis by activating the SIRT1/GPX4 pathway." (PMID 39872048, 2024). "Consequently, targeting Sirt1 through pharmacological modulators holds promise as a therapeutic approach for renal fibrosis." (PMID 39687299, 2024). "In addition, further researches are still needed to determine the exact mechanism of SIRT1 on GPX4 in renal fibrosis." (PMID 39872048, 2024). "Research indicates involvement of SIRT1/HIF-1α in renal fibrosis." (PMID 39335456, 2024). "Subsequent results confirmed that OA inhibited renal fibrosis by regulating Sirt1 activity." (PMID 39687299, 2024). "We then wondered whether OA plays a role in renal fibrosis by regulating Sirt1 levels in renal tubular epithelial cells." (PMID 39687299, 2024). "Studies have shown that SIRT1 exerts a protective effect in cardiac and renal fibrosis." (PMID 39727955, 2024). "Sirt1 ameliorated renal fibrosis by reducing endoplasmic reticulum stress." (PMID 39687299, 2024). "It is unrealistic to expect oral resveratrol to enhance SIRT1 activity and reduce renal fibrosis." (PMID 39335456, 2024). "Studies indicate that activating Sirt1 may mitigate renal fibrosis, as evidenced by its capacity to attenuate fibrosis by repressing HIF-2α." (PMID 39687299, 2024). "SIRT1 overexpression enhances renal function and reduces lipid accumulation and renal fibrosis." (PMID 39335456, 2024). "Our study indicated that OA might exert anti-renal fibrosis effects through the activation of Sirt1 and the suppression of the TGF-β/Smad3 signaling pathway." (PMID 39687299, 2024). "However, the inhibition of ferroptosis and renal fibrosis owing to DSI were reversed by SIRT1 inhibitor EX527." (PMID 39872048, 2024). "Salidroside also reversed STZ-induced reduction of nephrin and podocin expression while alleviating podocyte injury and renal fibrosis through activation of the Sirt1/PGC-1α signaling pathway, thus promoting mitochondrial biogenesis and exerting protective effects against DN." (PMID 38259279, 2023). "Additionally, SRT1720 also suppressed HIF1α, GLUT1, and SNAIL expressions both in vivo and in vitro, indicating a role for SRT1720 in the prevention of diabetes-induced renal fibrosis via the SIRT1/HIF1α/GLUT1/SNAIL pathway." (PMID 37371668, 2023). "Rhein can improve renal fibrosis by blocking SirT1/STAS3/Twist1/Cpt1a-depandent FAO dysfunction, which may also be one of the mechanisms for rhubarb drugs." (PMID 35408745, 2022). "They regulate multiple signaling pathways such as Wnt/β-catenin, TGF-β1/Smad, Akt/mTOR, CX3CL1-RAF/MEK/ERK, mTORC1/p70S6K, SIRT1-NF-κB, and interfere with different cytokine or inflammatory factors expression to regulate the development and progression of renal fibrosis." (PMID 36160409, 2022). "In addition, it has also been found that quercetin can inhibit tubular epithelial cell senescence and reduce renal fibrosis by activating SIRT1/PINK1/Parkin-mediated mitosis." (PMID 35978370, 2022). "Considering that activation of SIRT1 by resveratrol can alleviate renal fibrosis induced by UUO in mice, piceatannol may have a beneficial effect on renal fibrosis." (PMID 35277012, 2022).
renal fibrosis (continued). "The present study investigated whether an SIRT1/2 inhibitor, Tenovin-1, has a protective function against HFD-induced renal fibrosis and its underlying mechanisms." (PMID 36139886, 2022). "Studies have focused on the role of SIRT1 for renal fibrosis." (PMID 35795148, 2022). "SSR could contribute to renal protection by up-regulating SIRT1/Smad3 deacetylation pathway and attenuating renal fibrosis in 5/6 nephrectomy model of CKD." (PMID 35795148, 2022). "In diabetic models, SIRT1 prevent renal fibrosis by suppressing HIF1α, GLUT1, and SNAIL." (PMID 35874713, 2022). "Emerging studies have suggested a protective role of SIRT1 in the pathogenesis of renal fibrosis." (PMID 35874713, 2022). "For example, quercetin, a dietary flavonoid, can reduce RTEC senescence in renal fibrosis via SIRT1/PINK1/mitophagy axis, while liraglutide, a glucagon-like peptide-1 receptor agonist, can improve mitochondrial homeostasis in heart injury through the identical signaling axis." (PMID 34359852, 2021). "In mesangial cells, miR-34a-5p reduced SIRT1 expression and thus aggravated renal fibrosis." (PMID 34097717, 2021). "Furthermore, our previous results showed that, by inhibiting the transcriptional activity of Smad3, SIRT1 plays a protective role against renal fibrosis in a CKD rodent model." (PMID 33758176, 2021). "Therefore, in the following experiments, we focused our interest on the SIRT1/HIF-2α axis of renal fibrosis." (PMID 33758176, 2021). "Resveratrol, an anti-inflammatory and antioxidant polyphenol, inhibits renal fibrosis via the activation of SIRT1 and deacetylation of SMAD3 in UUO mice, and decreases the renal fibrosis caused by diabetic hyperglycemia activated renal fibroblasts via the inhibition of AMPK/NOX4/ROS signaling." (PMID 33163486, 2020). "SIRT1 up-regulation by resveratrol treatment ameliorated renal fibrosis in proximal tubular cells treated with TGF-β in addition to a mouse model of UUO; this was found to be due to inhibition of the EMT through deacetylation of Smad4 and inhibition of matrix metalloproteinase-7 (MMP-7)." (PMID 32932720, 2020). "In addition, kidney fibrogenesis was observed with the calcification and formation of calcium crystals in the kidney, and SIRT1 up-regulation induced by an SIRT1 activator can attenuate renal fibrosis and renal injury." (PMID 30714469, 2019). "Furthermore, the CKD model was developed based on blocking the activity of Sirt1, and it was observed that the dysfunction of Sirt1 plays an essential role in renal fibrosis." (PMID 28969091, 2017). "However, a recent study showed that renal fibrosis was inhibited by treatment of UUO mice with the SIRT1/2 inhibitor sirtinol or SIRT1 inhibitor EX527." (PMID 27902771, 2016). "Moreover, Sirt1 exerted powerful renoprotective effects by inhibiting renal fibrosis, reducing cell proliferation, and decreasing urine protein." (PMID 27034698, 2016). "Several pieces of evidence from our recent study suggest that RSV could decrease proteinuria and serum creatinine, attenuate renal pathological change and the expression of renal fibrosis gene through Sirt1 activation and reduced Smad3 acetylation." (PMID 27129290, 2016). "In addition, SalB mitigated EMT related to renal fibrosis via SIRT1-mediated autophagy." (PMID 40308781, 2025). "Emerging data indicate that upregulation of SIRT1 expression may mitigate renal fibrosis." (PMID 39335456, 2024). "In addition, Sirt1 is involved in activating PTEN-induced kinase 1 (PINK1)/Parkin-associated mitochondrial autophagy and is an effective therapeutic strategy for preventing renal fibrosis." (PMID 38347622, 2024).